LINC01605 (long independently transcribed non-coding RNA 1605)
Synonyms: ODIR1; lncGALM; LincDUSP; RP11-527N22.2; TCONS_00014973
Gene: Long non-coding RNA gene on chromosome 8 (37,406,399 to 37,625,873, reverse strand). Ensembl gene ENSG00000253161.
Diseases named in the same sentence as LINC01605 in open-access papers:
LINC01605 is named in the same sentence as 27 diseases in open-access papers, as found by Europe PMC text mining. Sharing a sentence is not in itself a finding about the gene and the disease. The quoted sentences say what the papers report.
colorectal cancer (6 papers, 2021 to 2025). A primary or metastatic malignant neoplasm that affects the colon or rectum. "The LINC00839 gene is most associated with nasopharyngeal carcinoma and neuroblastoma, while the LINC01605 gene is most associated with colorectal carcinoma and neoplasm." (PMID 41141624, 2025). "The function of LINC01605 has been reported in colorectal cancer, bladder cancer, breast cancer, nasopharyngeal carcinoma and squamous cell carcinoma." (PMID 39048994, 2024). "As a promising lncRNA, LINC01605 has been studied in breast cancer, colorectal cancer, bladder cancer, etc.; in these tumors, LINC01605 can promote cell proliferation and migration." (PMID 39048994, 2024). "For example, LINC01605 is highly expressed in colorectal cancer, and its expression correlates with tumor stage, lymph node metastasis, and distant metastasis of colorectal cancer patients." (PMID 37781524, 2023). "LINC01605 has been demonstrated in triple negative breast cancer, nasopharyngeal carcinoma, colorectal cancer, and other cancers to promote tumor proliferation and invasion through multiple pathways." (PMID 36188220, 2022). "LINC01605 is notably overexpressed in colorectal cancer tissues." (PMID 41141624, 2025). "Furthermore, analysis of genetic sequencing has identified genetic variations (e.g., in LINC01605, PROKR2, and CCSER1 genes) linked to constituents of the metabolome or microbiome, as well as the risk of adenoma or colorectal cancer." (PMID 37012201, 2023).
colon cancer (5 papers, 2018 to 2023). "So far, three studies have been published on LINC01605 (which is also referred to as lincDUSP) demonstrating its oncogenic role in colon cancer and in laryngeal squamous cell carcinoma by promoting cell proliferation, migration and invasion." (PMID 37762037, 2023).
breast carcinoma (2 papers, 2023 to 2024). "We also showed that the loss or downregulation of LINC01605 impairs cell migration in a breast cancer cell line." (PMID 37762037, 2023).
nasopharyngeal carcinoma (2 papers, 2022 to 2025). A carcinoma arising from the nasopharyngeal epithelium. "In nasopharyngeal carcinoma, LINC01605 similarly acts as an oncogene by enhancing cell proliferation and inhibiting apoptosis." (PMID 41141624, 2025).
Alzheimer disease (1 paper, 2025). A progressive, neurodegenerative disease characterized by loss of function and death of nerve cells in several areas of the brain leading to loss of cognitive function such as memory and language. "In this study, we predicted potential targets of LINC01605 using the ENCORI database, obtained Alzheimer's disease (AD)‐related genes from Genecards, and identified differentially expressed genes from the GSE107844 dataset." (PMID 41294029, 2025).
Aortic dissection (1 paper, 2025). Aortic dissection refers to a tear in the intimal layer of the aorta causing a separation between the intima and the medial layers of the aorta. "In this study, we identified LINC01605 as a novel long noncoding RNA (lncRNA) critically involved in the pathogenesis of aortic dissection (AD)." (PMID 41294029, 2025). "LINC01605 is upregulated in a mouse model of aortic dissection and participates in the cellular processes of migration, proliferation and autophagy associated with aortic dissection by modulating the expression of genes such as SGK1, MMP‐2, MMP‐9, α‐SMA, SM22α, LC3B and p62." (PMID 41294029, 2025). "Knockdown of LINC01605 can inhibit these processes, suggesting that LINC01605 may be a potential therapeutic target for the treatment of aortic dissection." (PMID 41294029, 2025). "Similarly, LINC01605 was overexpressed in VSMCs derived from patients with aortic dissection." (PMID 41294029, 2025). "Functionally, in vitro knockdown of LINC01605 reversed Ang II‐induced VSMC synthetic phenotype switching and matrix degradation, while in vivo silencing attenuated aortic dissection severity in preclinical models." (PMID 41294029, 2025).
colon adenocarcinoma (1 paper, 2025). "The expression of the LINC01605 gene was found to be upregulated in several cancers, including Colon Adenocarcinoma (COAD), ESCA, Head and Neck Squamous Cell Carcinoma (HNSCC), Lung Adenocarcinoma (LUAD), and Rectum Adenocarcinoma (READ)." (PMID 41141624, 2025).
pancreatic cancer (1 paper, 2024). "However, LINC01605 has not been studied in the field of pancreatic cancer, so we performed integrated analysis of clinical samples and RNA sequencing data and performed cellular function experiments and mouse model experiments to assess the role of LINC01605 in PDAC progression." (PMID 39048994, 2024).
renal carcinoma (1 paper, 2022). A carcinoma arising from the epithelium of the renal parenchyma or the renal pelvis. "The results showed that the mRNA expression of LINC01605, AGAP2-AS1, FOXD2-AS1, and LINC02195 in renal cancer cells was higher than that in normal renal cells." (PMID 36188220, 2022).
renal clear cell carcinoma (1 paper, 2024). "We designed siRNAs for LINC01138 and LINC01605 to silence the expression of LINC01138 and LINC01605 in human renal clear cell carcinoma cell lines 769-P and 786-O cells to investigate the roles of LINC01138 and LINC01605 in renal clear cell carcinoma." (PMID 39167430, 2024). "We experimentally confirmed the role of LINC01138 and LINC01605 in renal clear cell carcinoma." (PMID 39167430, 2024). "LINC01138 and LINC01605 knockdown inhibited the proliferation of renal clear cell carcinoma." (PMID 39167430, 2024).
cancer (7 papers, 2018 to 2025). A tumor composed of atypical neoplastic, often pleomorphic cells that invade other tissues. "This difference likely reflects the cancer-type-specific role of LINC01605, as lncRNAs can behave differently depending on the tumor context and gene regulation patterns." (PMID 41141624, 2025). "In NPC, the LINC01605/miR-942-5p/Ikbkb ceRNA network modulates cancer cell behavior, with LINC01605 facilitating the recruitment of IGF2BP2 to stabilize USP3." (PMID 38773075, 2024). "To confirm the impact of LINC01605 in cancer cell motility, we tested LINC01605-WT and KO cell ability to migrate across a transwell chamber using a fibronectin coating as an attractant." (PMID 37762037, 2023). "This would allow us to gain a better knowledge of the LINC01605 transcript and its regulation in different cancer types in which it acts as a potential oncogene." (PMID 37762037, 2023). "To start exploring LINC01605 function in cancer, we performed RNA-seq gene expression analysis in MDA-MB-231 LINC01605-WT and KO clones." (PMID 37762037, 2023). "The enrichment of EP300 or SMYD2 in the promoter region of LINC01605 were much higher in cancer tissues than that in ADJ tissues." (PMID 34544413, 2021). "Furthermore, LINC01605 increased cancer cell proliferation, migration, invasion, and decreased apoptosis through the miR-3960/SOX11 axis." (PMID 41141624, 2025). "Moreover, evidence suggests that LINC01605 influences cancer cell behavior through diverse signaling pathways." (PMID 41141624, 2025). "In addition, LINC01605 RNA may promote aerobic glycolysis, proliferation, migration, and invasion of cancer cells." (PMID 38727314, 2024).
tumor (6 papers, 2018 to 2025). "LINC01605 expression is upregulated in both PDAC primary tumor and liver metastasis tissues and correlates with poor clinical prognosis." (PMID 39048994, 2024). "Our results indicate that the upregulated lncRNA LINC01605 promotes PDAC tumor cell proliferation and migration by regulating cholesterol metabolism via activation of the mTOR signaling pathway in a LIN28B-interacting manner." (PMID 39048994, 2024). "RNA-seq of LINC01605-knockdown PDAC cells and subsequent inhibitor-based cellular function, western blotting, immunofluorescence and rescue experiments were conducted to explore the mechanisms by which LINC01605 regulates the behaviors of PDAC tumor cells." (PMID 39048994, 2024). "LINC01605-specific staining demonstrated that the expression level was increased in both the primary tumor and the liver metastasis tissues compared to that in the adjacent tissues." (PMID 39048994, 2024). "Taken together, these results reveal that LINC01605 facilitates tumor growth and liver metastasis of PDAC in vivo, which results in tumor growth and liver metastasis." (PMID 39048994, 2024). "The visual diminution in tumor sizes of the subcutaneous xenograft models intuitively reflected the restricted cellular proliferation of the LINC01605-knockdown Patu-8988 cells." (PMID 39048994, 2024). "Collectively, our study provides new insight into the role of LINC01605 in PDAC tumor growth and liver metastasis, which suggests its clinical value against the deadly disease." (PMID 39048994, 2024). "We analyzed the H3K27ac or H3K4me3 recruitment levels of LINC01605 promoter in tumor tissues and ADJ tissues of four CC patients using ChIP-qPCR." (PMID 34544413, 2021). "Their staining intensities in tumor tissues were significantly higher than that in ADJ tissues, and the staining H-scores was positively correlated with the LINC01605 expression in tumor tissues." (PMID 34544413, 2021). "The expression of LINC01605 had a significant positive correlation with immune cell infiltration in the tumor tissues of COAD patients in the TCGA database." (PMID 34544413, 2021). "Later, overexpression plasmids of SMYD2 and EP300 successfully abrogated the anti-tumor effects of sh-LINC01605 in vitro, which corroborated our theory again." (PMID 34544413, 2021). "Consistent with the role reported for these miRNAs in most previous studies, the miRNAs identified in our analysis as potential downstream targets of LINC00839 and LINC01605 may function as tumor suppressors in EC." (PMID 41141624, 2025). "Altogether, these data and results suggest that LINC01605 may act as a key factor in the process of PDAC tumor growth and liver metastasis." (PMID 39048994, 2024). "Despite these findings, whether LINC01605 regulates tumor cells via the mTOR signaling pathway remains unclear." (PMID 39048994, 2024). "Additionally, the upregulation of LINC01605 expression in PDAC tumor tissues was further verified by expression analysis of the TCGA & Genotype-Tissue Expression (GTEx) PAAD datasets." (PMID 39048994, 2024). "Moreover, the staining intensity of SPTBN2 in tumor tissues was positively correlated with the staining intensity of LINC01605." (PMID 34544413, 2021). "In the tumor immune microenvironment, high expression of LINC01138 and LINC01605 showed low tumor purity, high immune score, high stromal score and high ESTIMATE score." (PMID 39167430, 2024). "LINC01605, SNHG20, LUCAT1, and ZNF337-AS1 had significantly high expression in tumor tissues, while MEG9, LINC01082, and DICER1-AS1 had high expression in ADJ tissues." (PMID 34544413, 2021). "The m6A modification of SPTBN2 was much higher in tumor tissues than that in ADJ tissues, which was positively correlated with the LINC01605 expression." (PMID 34544413, 2021).
tumor (continued). "Importantly, we found that LINC01605 promotes PDAC progression through mTOR signaling pathway activation, which further regulates cholesterol metabolism and thus leads to PDAC tumor growth and liver metastasis; we also found that it may interact with LIN28B." (PMID 39048994, 2024).
LINC01605 also shares sentences with these, for which no sentence is quoted: adenoma (2 papers); adenocarcinoma (1); bladder cancer (1); dissection (1); endometrial carcinoma (1); esophageal cancer (1); Fanconi anemia (1); head and neck squamous cell carcinoma (1); laryngeal squamous cell carcinoma (1); lung adenocarcinoma (1); neuroblastoma (1); ovarian carcinoma (1); pancreatic ductal adenocarcinoma (1); rectum adenocarcinoma (1); triple-negative breast carcinoma (1).